IDO1 (indoleamine 2,3-dioxygenase 1)
Diseases named in the same sentence as IDO1 in open-access papers (continued):
Sharing a sentence is not in itself a finding about the gene and the disease.
systemic lupus erythematosus (17 papers, 2012 to 2026). An autoimmune multi-organ disease typically associated with vasculopathy and autoantibody production. "CD19+ DCs expressing IDO1 also expanded in spleens of aged lupus-prone Nba2 mice and during chronic retroviral infections in mice." (PMID 32625215, 2020). "Our preliminary data similarly suggest elevated IDO1 expression in SigH+ pDCs in both B6.Nba2 and lupus-prone (NZB x NZW)F1 mice." (PMID 31555267, 2019). "To establish if IDO was dysregulated in lupus-prone B6.Nba2 mice, we tested basal levels of IDO1 and IDO2 in spleens from unmanipulated female B6.Nba2 strains and control age- and sex-matched B6 mice." (PMID 31555267, 2019). "In summary, we have here shown that B6.Nba2 lupus-prone mice express elevated levels of IDO1 and increased total IDO enzymatic activity." (PMID 31555267, 2019). "Corresponding with a previous report in the MRLlpr/lpr mouse model of lupus, we found elevated levels of IDO1 and increased total IDO enzymatic activity in spleen tissue from lupus-prone female B6.Nba2 mice as compared with non-autoimmune prone female B6 mice." (PMID 31555267, 2019). "We show here that IDO1 protein and total IDO enzymatic activity are significantly elevated in lupus-prone B6.Nba2 mice relative to B6 controls." (PMID 31555267, 2019). "With respect to systemic lupus erythematosus, IDO1-KO mice that were chronically exposed to apoptotic cells developed a lupus-like syndrome and pharmacological inhibition of IDO accelerated disease in the MRL-lpr mouse model for spontaneous lupus." (PMID 26914138, 2016). "Similarly, IDO1 is overexpressed in spleens from MRLlpr lupus-prone mice." (PMID 31555267, 2019). "In conclusion, both levels of IDO1 and total IDO enzymatic activity were found to be elevated in spleens from lupus-prone B6.Nba2 mice." (PMID 31555267, 2019).
Stroke (16 papers, 2015 to 2025). Sudden impairment of blood flow to a part of the brain due to occlusion or rupture of an artery to the brain. "IDO1, one of the key enzymes of the kynurenine metabolic pathway, has increased activity after stroke onset and is associated with an increased risk of death." (PMID 40556758, 2025). "We found that those IDO1 variants which show a trend towards elevated mRNA level are more frequent in stroke patients than in controls." (PMID 34680558, 2021). "Our results are important novel observations which suggest a causal relationship between elevated IDO1 expression and stroke etiology." (PMID 34680558, 2021). "IDO1 variants showing a trend towards elevated mRNA level were more frequent in stroke patients than in controls, while IDO1 variants which lead to a trend of decreasing mRNA level are present among stroke patients less frequently than in non-stroke controls." (PMID 34680558, 2021). "These are important novel observations as thought elevated IDO1 expression in stroke has been described earlier our report is the first suggesting causal relationship between IDO1 and stroke etiology." (PMID 34680558, 2021). "In our study, we confirmed the link between a reduced risk of stroke and the frequency of the C/C-C/C genotype of the c.-1493G>C – IDO1 (rs10089084) and c.-1449C > A – TPH2 (rs7963803) polymorphisms." (PMID 31817010, 2019). "Furthermore, single-nucleotide polymorphisms of the genes encoding the tryptophan metabolism enzymes, such as TPH1, TPH2, KAT1, KAT2, and IDO1, were found to seriously influence the risk and pathogenesis of stroke." (PMID 39195495, 2024). "Despite the robust association of pro-inflammatory cytokines with the occurrence of PSD, it is unclear whether the effect of increased immune activation resulting from stroke on the risk of PSD is associated with IDO1 expression." (PMID 36911716, 2023). "The present study examined for the first time the role of gene polymorphisms of IDO (IDO1 and IDO2) and its inducer and serum IDO1 levels in the risk of PSD at 2 weeks after stroke onset and also discussed the relationship between cytokine SNPs and serum IDO1 levels." (PMID 36911716, 2023). "Based on these findings, IDO1 may be a pivotal mediator of the contribution of stroke-associated inflammatory processes to the development of PSD." (PMID 36911716, 2023). "IDO1 was inversely associated with ischemic heart disease with a directionally consistent estimate for stroke and might be a potential therapeutic target for this disease." (PMID 36879035, 2023). "In addition, we observed that the C/C-C/A genotype of c.975-7T > C– KAT2 (rs1480544) and– c.-1849C > A IDO1 (rs3824259) SNPs was associated with an increased risk of stroke." (PMID 31817010, 2019). "Moreover, in the case of the c.-1493G > C – IDO1 (rs10089084) polymorphism, the G/G genotype and the G allele were linked with an increased frequency of stroke occurrence as compared to the control subjects, whereas the C/C homozygote and the C allele reduced this risk." (PMID 31817010, 2019). "IDO1 upregulation was always observed in various inflammatory states, including stroke, when the IDO1 mRNA levels increased at an early phase." (PMID 39195495, 2024). "Stroke patients with the TNF-α rs361525 G/G genotype had higher serum IDO1 levels compared to those with the G/A genotype (Z = -2.451, p = 0.014)." (PMID 36911716, 2023). "PSD occurs in approximately one-third of stroke survivors and is characterized by increased levels of IDO1 in microglia in the brain." (PMID 37190515, 2023). "The available results, furthermore, reveal that upregulation of IDO1 activation is a characteristic of the post-stroke inflammatory response." (PMID 36911716, 2023). "Each of these is located in intronic regions and has been suggested by previous studies to occur with different frequencies in relation with stroke and/or have an impact on IDO1 mRNA levels." (PMID 34680558, 2021).
Stroke (continued). "Together, the results in this part suggested that the increased IDO1 expression on pDCs is critical for Tregs priming under the pathology of stroke." (PMID 32076400, 2020). "This in vivo study provided evidence that the IDO1-dependent neurotoxic kynurenine metabolism represented a potential therapeutic target for the treatment of post-stroke dementia." (PMID 33192328, 2020). "Following cerebral ischemia, levels of IDO1 in infarct and penumbra regions are reported to increase at 24 h after stroke." (PMID 32076400, 2020). "The C/C-G/T, C/A-G/T and A/A-G/T combined genotypes of c.-1849C>A – IDO1 (rs3824259) and c.-844G > T – TPH2 (rs4570625) caused a reduction of the stroke risk in the Polish population." (PMID 31817010, 2019). "We found that the G/C-T/T, C/C-T/T and C/C-T/A genotypes of c.-1493G > C – IDO1 (rs10089084) and c.-1668T>A – TPH1 (rs623580) reduced the risk of stroke, whereas the G/G-T/A genotype increased this risk." (PMID 31817010, 2019). "On the one hand, we observed that the G/C-G/G combined genotype of the c.-1493G > C – IDO1 (rs10089084) and c.-844G > T – TPH2 (rs4570625) polymorphisms were associated with an increased risk of stroke." (PMID 31817010, 2019). "In the case of the c.-1849C > A – IDO1 (rs3824259) and c.804-7C > A – TPH1 (rs1799913) polymorphisms, the C/C-C/A and C/A-C/A combined polymorphisms were linked with a reduction of stroke risk about 20 times (p = 0.004) and 10 times (p < 0.001), respectively." (PMID 31817010, 2019). "The C/C-T/T and C/A-T/T genotypes of c.-1849C>A – IDO1 (rs3824259) and c.-1668T > A – TPH1 (rs623580) were associated with a reduced risk of stroke, whereas the C/A-T/A and C/A-A/A genotypes caused an increase of the risk in the Polish population." (PMID 31817010, 2019). "Serum IDO1 levels were significantly higher in stroke patients carrying the TNF-α rs361525 G/G genotype than in those carrying the G/A genotype (Z = -2.451, p = 0.014), indicating that TNF-α rs361525 polymorphism was associated with serum IDO1 levels." (PMID 36911716, 2023). "The activity of IDO1 has been reported to be elevated in stroke patients." (PMID 32076400, 2020). "Additionally, we found that the only C/A-T/T genotype of the c.-1849C > A – IDO1 (rs3824259) and c.-173A>T – TPH1 (rs10488682) combined polymorphisms elevated the risk of stroke development." (PMID 31817010, 2019). "Moreover, we found that the G/G-T/T, G/G-C/C and G/C-C/C genotypes of c.-1493G>C – IDO1 (rs10089084) and c.975-7T > C– KAT2 (rs1480544) increased the risk of stroke about four times (p = 0.009), 18 times (p < 0.001) and three times (p < 0.001), respectively." (PMID 31817010, 2019). "The G/G-A/T and G/G-T/T genotypes of c.-1493G>C – IDO1 (rs10089084) and c.-173A > T – TPH1 (rs10488682) caused an increase of the risk of stroke, whereas the C/C-A/T and C/C-T/T genotypes of the same combined polymorphisms brought about a reduction of this risk." (PMID 31817010, 2019). "This gives ground to the notion that IDO1 inhibitor therapy after the ischemic event could be beneficial against stroke-induced immunodepression and could help to decrease the occurrence of the so often fatal post-stroke infections." (PMID 34680558, 2021). "Noteworthy is that association of these IDO1 variants with stroke is recognizable primarily in groups of patients with advanced age, altered WBC and CRP levels and with particular stroke etiology, all of which could be directly related with altered IDO1 functions." (PMID 34680558, 2021). "Consistent with animal experiments and evolutionary biology, we obtained genetic validation of plasma IDO1 protein as protecting against IHD, with directionally consistent results for stroke." (PMID 31186442, 2019). "Moreover, the frequency of the C/C-C/A genotype of c.-1849C > A – IDO1 (rs3824259) and c.-1449C>A - TPH2 (rs7963803) was decreased, while the C/A-C/C genotype was increased in the patients after a stroke as compared to the healthy volunteers." (PMID 31817010, 2019).
Stroke (continued). "In accord with changes of metabolite levels, activities of KP enzymes differed as well: IDO1, KMO, 3-hydroxyanthranilate 3,4-dioxygenase (3-HAO) and the composed 3-HAO and aminocarboxymuconate semialdehyde decarboxylase (ACMSD) activity was higher in stroke patients compared to controls." (PMID 34680558, 2021). "Furthermore, we examined the mRNA levels of TPH1, IDO1 and KYAT1 genes in peripheral venous blood with the aim of assessing (i) whether there are changes in their expression during the course of stroke and (ii) does any of their investigated SNPs have an impact on gene expression." (PMID 34680558, 2021).
thyroid cancer (15 papers, 2009 to 2025). "IDO1 gene expression was higher in the thyroid carcinoma tissue compared with normal thyroid, and it was associated with Foxp3+ Tregs density in the tumor microenvironment." (PMID 34576041, 2021). "A possible positive association between the immunohistochemical expressions of PD-L1 and IDO1 has also been observed in poorly differentiated thyroid carcinomas." (PMID 39273017, 2024). "IDO1 was also expressed in human thyroid cancer cell lines in vitro, and in a cell line with the highest IDO1 expression, the increased KYN level was also detected in the cell culture medium, indicating functional IDO1 activity." (PMID 34576041, 2021). "The authors showed an up-regulation of IDO1 in all the histotypes of thyroid cancer analyzed respect to the normal tissue, with mRNA expression levels highest in ATC, followed by MTC and finally PTC." (PMID 33986723, 2020). "Elevated levels of IDO1 have been observed in many human cancers, such as in ovarian cancer, in colon cancer, in breast cancer and even in thyroid cancer." (PMID 33986723, 2020). "We have previously demonstrated that IDO1 is up-regulated in thyroid cancers and contributes to the creation of an immunosuppressant environment." (PMID 31936153, 2020). "Moretti and colleagues analyzed IDO1 expression in a collection of thyroid cancers (105 PTCs, 11 MTCs, and 6 ATCs)." (PMID 33986723, 2020). "To deeper investigate the role of the IDO1-Kynurenine-AhR pathway in thyroid cancer pathogenesis, we analyzed AhR expression in human-derived thyroid cancers and in thyroid tumors from BRAF-transgenic mice." (PMID 31936153, 2020). "To more deeply investigate the role of IDO1-kynurenine-AhR in thyroid cancer, we analyzed AhR expression in a collection of tissues (90 PTCs, 11 MTCs and 6 ATCs) as mRNA or, in a subgroup of 41 PTCs, as protein." (PMID 31936153, 2020). "Accordingly, IDO1 was infrequently expressed in isolation but was more frequently co-expressed in cases with PD-L1 positivity, which has been confirmed in thyroid carcinoma as well." (PMID 30717285, 2019). "Additionally, the IDO1-Kyn-AhR pathway is a critical regulator of the immunosuppressive microenvironment and favors the acquisition of a mesenchymal phenotype in thyroid cancer." (PMID 36831659, 2023). "It has been confirmed that the IDO1–Kyn–ligand-activated transcription factor (AhR) pathway in thyroid cancer cells would facilitate epithelial-to-mesenchymal transition (EMT), while Kyn depletion in vivo would reverse IDO1-mediated cancer immune suppression in an animal model." (PMID 35003126, 2021). "Findings of a direct correlation between RET/PTC3 and IDO1 and between BRAFV600E and PD-L1 suggest that different driver mutations associated with different subtype of thyroid cancer contribute to different microenvironments and differential recruitment of cells to thyroid tumors." (PMID 33986723, 2020). "Moreover, FTC-133 cells express the highest level of IDO1 among thyroid cancer lines." (PMID 41262240, 2025). "This study confirmed the importance of the IDO1-Kyn-AhR pathway in thyroid cancer tumorigenesis, suggesting an AhR pivotal role in mediating an immunosuppressive microenvironment and favoring the acquisition of a mesenchymal phenotype that could promote invasiveness and metastasis." (PMID 31936153, 2020). "We thus narrowed our investigational field to the thyroid cancer line FTC-133 after exposure to the three catalytic inhibitors, to deep inside the post-translational mechanism by which the IDO1 catalytic inhibitors increase the protein level in the tumor cells." (PMID 41262240, 2025). "Subsequently, Moretti and coworkers proved that RET/PTC3 induces IDO1 expression through full activation of STAT1-IRF1 pathway, demonstrating a direct link between this immunosuppressive enzyme and the oncogenic activation of RET in thyroid carcinoma." (PMID 33986723, 2020).
thyroid cancer (continued). "Authors demonstrated that IDO1 expression was elevated in thyroid carcinoma compared to normal thyroid tissue." (PMID 25328756, 2014). "Besides, thyroid cancer cells upregulated negative immune checkpoints, such as CTLA-4 (cytotoxic T-lymphocyte associated protein 4) and PD-L1 (programmed death-ligand 1), as well as immunosuppressive enzymes (IDO1, indoleamine 2,3-dioxygenase 1)." (PMID 37434155, 2023). "In the thyroid carcinoma cell line FTC-133, the stabilized and non-enzymatic IDO1 protein promotes the proliferation and migration of the tumor, resulting in an adverse pro-tumorigenic effect." (PMID 41262240, 2025).
triple-negative breast carcinoma (14 papers, 2018 to 2026). An invasive breast carcinoma which is negative for expression of estrogen receptor (ER), progesterone receptor (PR), and human epidermal growth factor receptor 2 (HER2). "Furthermore, an increased expression of IDO1 was found in triple-negative breast cancers and was associated with PD-L1 co-expression, suggesting that IDO1 might be a mechanism of anti-PD-1/PD-L1 immunotherapy resistance." (PMID 37408267, 2023). "In triple-negative breast cancer, Indoleamine 2,3 – Dioxygenase 1 (IDO-1) upregulation increases HLA-G expression, thereby suppressing NK cell antitumor activity; blockade of IDO-1 can restore NK cell cytotoxicity." (PMID 41445738, 2025). "As reported by a phase I/II trial (NCT02178722), a novel combined therapy of epacadostat (IDO1 inhibitor) and pembrolizumab (PD-1 inhibitor) was well tolerated and showed antitumor activity in patients with triple-negative breast cancer." (PMID 36765782, 2023). "The Cancer Genome Atlas (TCGA) database analysis reveals that the expression level of IDO1 is significantly upregulated in triple-negative breast cancer (TNBC) compared to normal breast tissue." (PMID 36550159, 2022). "Another immunoinhibitory pathway of interest is IDO1, a rate-limiting oxidoreductase, which is currently being explored as part of combined photodynamic therapy and checkpoint blockade immunotherapy for triple-negative breast cancer." (PMID 37483962, 2023). "In conclusion, Schisandrin A exhibits potential anti-triple-negative breast cancer (TNBC) effects by modulating and regulating diverse pathways, including GSK3B and IDO1, alongside its impact on the cell cycle and immune microenvironment." (PMID 42220063, 2026). "This system delivers CRISPR/Cas9 directly to tumor cells to knock down indoleamine 2,3-dioxygenase-1 (IDO1), a key immunosuppressive mediator often upregulated in aggressive cancers like triple-negative breast cancer." (PMID 40377870, 2025).
type 1 diabetes (14 papers, 2015 to 2025). "For example, altered IDO levels have been found in patients suffering from Type 1 diabetes, with IDO1 being physiologically highly expressed in pancreatic islets β-cells of healthy tissue, but absent in the remainder." (PMID 34819875, 2021). "It has to be noted that the mechanisms of IDO1 actions could be different in an autoimmune context such as type I diabetes, where the observed low level of IDO1 may weaken the immunomodulatory microenvironment, and make the pancreatic β-cells more susceptible to inflammatory deleterious response." (PMID 31552046, 2019). "A previous study showed that the DCs vaccine used to inhibit type 1 diabetes activated IDO1 expression in vivo by stimulating the nonclassical NF-κB pathway, which led to the suppression of DC-mediated type 1 diabetes autoimmunity." (PMID 40688069, 2025). "A chimeric protein vaccine composed of the cholera toxin B subunit fused to proinsulin (CTB-INS) is shown to suppress type 1 diabetes (T1D) onset in NOD mice and upregulate the biosynthesis of the tryptophan catabolic enzyme indoleamine 2,3-dioxygenase (IDO1) in DCs." (PMID 33294443, 2020). "A chimeric protein vaccine composed of the cholera toxin B subunit fused to proinsulin (CTB-INS) was shown to suppress type 1 diabetes onset in NOD mice and upregulate biosynthesis of the tryptophan catabolic enzyme indoleamine 2, 3-dioxygenase (IDO1) in human dendritic cells (DCs)." (PMID 26881431, 2016). "IDO1 is defective in DCs of non-obese diabetic (NOD) mice, an experimental model of human autoimmune diabetes (type 1 diabetes or T1D), and maneuvers aimed at enhancing its expression and activity will exert therapeutic effects in prediabetic and also overtly diabetic animals." (PMID 31354721, 2019).